MGP (matrix Gla protein)
Diseases named in the same sentence as MGP in open-access papers (continued):
Sharing a sentence is not in itself a finding about the gene and the disease.
glaucoma (4 papers, 2018 to 2025). Increased pressure in the eyeball due to obstruction of the outflow of aqueous humor. "A recent study has shown that a Matrix Gla–Cre (MGP-Cre) mouse line exhibits Cre activity in the TM and other ocular cells relevant to glaucoma pathology." (PMID 39836483, 2025). "A novel MGP transgenic mouse model allows visualising angiogenesis- and glaucoma-relevant tissues by natural fluorescence." (PMID 30305657, 2018). "MGP is also one of the most abundant genes in the trabecular meshwork, the eye tissue responsible for maintenance of intraocular pressure (IOP) and development of Glaucoma." (PMID 33122788, 2020). "To assess whether specific alterations described in glaucoma were present in the HTM-3 cells, we evaluated the expression of Matrix Gla Protein (MGP) and Endothelial-Leukocyte Adhesion Molecule 1 (ELAM-1)." (PMID 30931966, 2019). "Standard PCR was performed to verify the size of all amplified products and amplification of ELAM-1, MGP and MYOC glaucoma-related genes was checked by sequentiation (data not shown)." (PMID 30931966, 2019).
glioma (4 papers, 2009 to 2022). A benign or malignant brain and spinal cord tumor that arises from glial cells (astrocytes, oligodendrocytes, ependymal cells). "Among the glioma cell lines used in the experiment, those with knocked down MGP gene presented decreased cell migration ability when compared to cells overexpressing MGP." (PMID 30257426, 2018). "To examine the functional role of MGP in glioma cell migration, we first performed siRNA mediated MGP knockdown experiments with U373fast, H4 and U343MG cell lines." (PMID 19712474, 2009). "In conclusion, we have demonstrated that MGP is overexpressed in glioma cells, while siRNA mediated knockdown leads to decreased glioma cell migration." (PMID 19712474, 2009). "Knockdown of MGP using siRNA in three different glioma cell lines led to decreased cell migration as demonstrated using two different migration assays, whereas proliferation remained unchanged." (PMID 19712474, 2009). "Several of the components identified in glioma ECMs are permissive substrates enhancing cell migration, but like the interaction of MGP and vitronectin, effects can be modulated by additional ligands or modifications." (PMID 19712474, 2009). "Immunohistochemistry verified positivity of glial tumor cells for MGP." (PMID 19712474, 2009). "Furthermore, human glioma cells, selected for high migration capacity (U373fast) showed elevated MGP expression compared to their less migrating counterparts (U373slow)." (PMID 19712474, 2009). "Like MGP, vitronectin expression in gliomas is known to increase with tumor grade in vivo." (PMID 19712474, 2009). "Because virtually nothing is known about the mechanisms linking upregulation of MGP and prognosis in gliomas and, more generally, about the function of MGP in tumors, we hypothesized that MGP promotes glioma migration and performed expression and migration analyses." (PMID 19712474, 2009). "In bioinformatics analysis, we took the intersection of upregulated genes identified in TCGA-GBM dataset, TCGA-LGG dataset, and the GSE140746 microarray, four glioma-related candidate genes were thereupon obtained, namely AQP4, BIRCS, MAGT1, and MGP)." (PMID 35416125, 2022). "We also investigated the glioma cell lines 86HG39, U343MG and non selected U373MG and could verify MGP protein expression in the supernatants using ELISA." (PMID 19712474, 2009).
idiopathic pulmonary fibrosis (4 papers, 2020 to 2024). Idiopathic pulmonary fibrosis (IPF) is a nonneoplastic pulmonary disease that is characterized by the formation of scar tissue within the lungs in the absence of any known cause. "In a different mouse model, the targeted removal of the MGP gene in specific cells resulted in the development of severe pulmonary fibrosis." (PMID 38066767, 2023). "It is also suspected that the compromise of the MGP carboxylation by VKA is involved in the onset of idiopathic pulmonary fibrosis since elastic fibers have a strong affinity with calcium." (PMID 33374341, 2020). "We have reported that lack of MGP in pulmonary ECs, where MGP is expressed at low levels, still caused ECs to undergo unwanted differentiation to contribute myofibroblasts to pulmonary fibrosis." (PMID 38781032, 2024). "It has also been proposed that vitamin K might slow the progression of idiopathic pulmonary fibrosis through the activation of MGP." (PMID 35159124, 2022).
lung carcinoma (4 papers, 2021 to 2024). "In recent years, the involvement of the VKDPs in lung cancer has become intensely studied, with recent studies reporting especially the role in tumor progression of Gas6 and MGP." (PMID 35053080, 2022). "Considering the role of these three molecules in lung cancer pathology, the main goal of this study was to assess their serum concentration before and after treatment and investigate how MGP, Gas6, EGFR, and VK1 are modified after one cycle of chemotherapy." (PMID 35053080, 2022). "MGP expression was found to be reduced during the symptomatic illness stage in lung cancer." (PMID 35354498, 2022).
uremia (4 papers, 2013 to 2023). A clinical syndrome associated with the retention of renal waste products or uremic toxins in the blood. "The fully inactive form of MGP, dp-ucMGP, reflects vitamin K deficiency and has been shown to be a reliable marker of arterial calcification and stiffness in various settings, including uremia." (PMID 36837922, 2023). "Therefore, the interplay between vitamin K and D is more pronounced in uremia and supplementation of active vitamin D compounds might contribute to the preservation of MGP activity and improve vascular health in CKD and HD." (PMID 32839405, 2020).
colitis (3 papers, 2018 to 2022). Inflammation of the colon. "We also examined SGK1, CEP55, ACSL1, OLFM4, DPP10, and MGP expression in the colon tissues of dextran sodium sulfate‐induced colitis mice." (PMID 34939750, 2022). "In addition, we also examined the expression of SGK1, CEP55, ACSL1, OLFM4, DPP10, and MGP in the colon tissues of dextran sulfate sodium‐induced colitis mice." (PMID 34939750, 2022). "In addition, we also examined the expression of SGK1, CEP55, ACSL1, OLFM4, DPP10, and MGP in the colon tissues of DSS‐induced colitis mice." (PMID 34939750, 2022). "Moreover, MSC-derived MGP alleviated the clinical and histopathological severity of colonic inflammation in mouse experimental colitis models to a remarkable degree." (PMID 35069573, 2021). "Moreover, MGP alleviated the clinical and histopathological severity of colonic inflammation in mouse experimental colitis models to a remarkable degree." (PMID 29880866, 2018). "To verify whether MGP contributes to the therapeutic effect of MSCs in vivo, we established the experimental colitis mouse model with 2,4,6-trinitrobenzene sulfonic acid (TNBS), which shows symptoms similar to clinical CD27,28." (PMID 29880866, 2018). "The results showed that MSCs-secreted MGP could ameliorate the clinical and histopathological severity of colonic inflammation, with an obvious inhibiting action on the number of T cells and degree of cytokine production in peritoneal lavage fluid and colon tissues of colitis mice." (PMID 29880866, 2018). "To further confirm the differential expression of these candidate genes between ulcerative colitis and normal groups, we determined the mRNA expression of SGK1, CEP55, ACSL1, OLFM4, MGP, and DPP10 in colon tissues of DSS‐induced colitis mice." (PMID 34939750, 2022). "The expression of MGP, which can be upregulated by a conserved binding site for Egr-1 in the upstream region of the human MGP gene, was positively correlated with disease severity of UC patients and DSS-induced colitis rats." (PMID 35069573, 2021). "Together, these results indicate that MSC-derived MGP may alleviate the status of T cells infiltration and suppress the expression of pro-inflammatory cytokines in colon tissues of TNBS-induced the experimental colitis mouse model." (PMID 29880866, 2018).
Crohn disease (3 papers, 2023 to 2024). A gastrointestinal disorder characterized by chronic inflammation involving all layers of the intestinal wall, noncaseating granulomas affecting the intestinal wall and regional lymph nodes, and transmural fibrosis. "Notably, MGP has shown potential as a novel and significant mediator for mesenchymal stem cell-mediated immunoregulatory treatment in Crohn’s disease, as indicated by recent research." (PMID 37777759, 2023). "In addition, MGP, whose expression was upregulated in CD73+ cell spheroids, reportedly ameliorates pathogenesis in a mouse model of Crohn’s disease through its MSC-derived immunomodulatory function that suppresses T cell proliferation and cytokine production." (PMID 36986706, 2023).
myocardial infarction (3 papers, 2020 to 2022). Gross necrosis of the myocardium, as a result of interruption of the blood supply to the area, as in coronary thrombosis. "The polymorphisms of the MGP gene were suggested to attribute to an increased risk of plaque calcification and myocardial infarction." (PMID 35935627, 2022). "However, pre-clinical studies have shown upregulated gene expression of MGP 24 h after myocardial infarction and peaking after 4 weeks, which might indicate that MGP is involved in or is a biomarker for post-infarction myocardial remodelling." (PMID 34444740, 2021).
nephrotic syndrome (3 papers, 2019 to 2020). A collection of symptoms that include severe edema, proteinuria, and hypoalbuminemia; it is indicative of renal dysfunction. "In rats, after 5/6 nephrectomy, renal expression of MGP was upregulated, and in human kidney tissues obtained from biopsies due to nephrotic syndrome, eGFR was inversely associated with glomerular and tubulointerstitial MGP expression." (PMID 32839405, 2020). "In the same study, the correlation with the MGP levels was investigated by using the information from the kidney biopsies and indicated that eGFR was inversely associated with tubulointerstitial and glomerular MGP mRNA expression in patients with nephrotic syndrome." (PMID 32824773, 2020). "The recent Nephrotic Syndrome Study Network cohort study reported that renal MGP expression increased in 5/6 nephrectomy rats." (PMID 32824773, 2020).
Obesity (3 papers, 2016 to 2024). Accumulation of substantial excess body fat. "In the present study, we analysed the association of serum inactive MGP with obesity, and found that dp-ucMGP is positively associated with central obesity." (PMID 32000575, 2020). "Given the essential function of MGP in fat metabolism, we analysed the association of serum dp-ucMGP level and obesity in human." (PMID 32000575, 2020). "Seeking a potential association between MGP expression and several CVD risk factors such as obesity, studies on mouse 3T3-L1 pre-adipocytes found increased levels of both mRNA for MGP and MGP protein itself, following stimulation of adipogenesis." (PMID 38542487, 2024). "Matrix Gla protein (MGP), Noggin, Sclerostin (SOST), and Gremlin have been identified as several extracellular, intracellular and transcriptional BMP inhibitors that are upregulated in obesity and act as negative regulators of BMP signaling pathways, ultimately downregulating osteoblastogenesis." (PMID 27746742, 2016). "However, until now there is no study reporting the correlation of MGP with obesity." (PMID 32000575, 2020).
Osteopenia (3 papers, 2020 to 2023). Osteopenia is a term to define bone density that is not normal but also not as low as osteoporosis. "Mice deficient in MGP display significant artery calcification and suffer pathological cartilage calcification causing osteopenia and fractures." (PMID 32584873, 2020).
Pulmonary artery stenosis (3 papers, 2014 to 2021). An abnormal narrowing or constriction of the pulmonary artery, in the main pulmonary artery and/or in the left or right pulmonary artery branches. "Deficiency of another VKDP, MGP, has also been associated with cardiac involvement, including pulmonary artery stenosis and ventricular septal defects." (PMID 28125048, 2017).
arteriovenous malformation (2 papers, 2023 to 2024). "Since loss of MGP is known to cause arteriovenous malformations in organs such as the brain, lungs, kidneys, and retina, we tested if arteriovenous (AV) shunting was also present in iBAT." (PMID 38184275, 2024).
asthenozoospermia (2 papers, 2019 to 2024). "To check whether mutations of human VKD MGP and GGCX affect male fertility, we screened for potential mutations in the exons of MGP and GGCX in a cohort of 199 patients with idiopathic asthenozoospermia and 110 fertile controls." (PMID 30981116, 2019).
breast invasive carcinoma (2 papers, 2021 to 2022). "Further verification of MGP is required in metastatic lesions as well as special types of invasive breast carcinoma, such as salivary gland-type tumors and neuroendocrine carcinoma." (PMID 36284362, 2022). "Through bioinformatic analysis, we identified MGP as a novel IHC marker supporting breast origin, demonstrating relatively high sensitivity and specificity for invasive breast carcinoma of no special type." (PMID 36284362, 2022).
calcinosis (2 papers, 2018 to 2020). Deposition of calcium in the tissues. "A possible explanation for this observation may be that the gamma-carboxylation of MGP is required to prevent calcinosis by binding and inhibiting calcification-inducible factors." (PMID 32640520, 2020). "Next to the autoantibody NXP2, which is prognostic for the development of calcinosis, phosphorylated matrix Gla protein was shown to be higher in patients with calcinosis than without calcinosis." (PMID 30619311, 2018). "Furthermore, it was found that MGP expression is upregulated in the skin of lcSSc patients with calcinosis compared to those without calcinosis." (PMID 32640520, 2020).
calculus (2 papers, 2012 to 2017). "Genetic polymorphisms may influence the ability of matrix Gla protein to bind calcium-containing crystals, which has been linked to increased vascular calcification and formation of urinary stones." (PMID 23284864, 2012).
Cerebral arteriovenous malformation (2 papers, 2021 to 2024). "MGP deficiency in mice is associated with the medial calcification of arterial walls and cerebral arteriovenous malformations.[28c] On the other hand, the biphasic expression pattern of MGP is required for normal chondrocyte differentiation in mammalian growth plate tissue." (PMID 38588510, 2024). "Deficiency in MGP induces vascular calcification and cerebral arteriovenous malformations." (PMID 34502527, 2021).
colorectal adenocarcinoma (2 papers, 2020 to 2022). The most common type of colorectal carcinoma. "used 80 pairs of colorectal adenocarcinoma tissues to show that the mRNA level of MGP was reduced in CRC (79%) compared to adjacent normal tissues by northern blot." (PMID 32405535, 2020).
dyslipidemia (2 papers, 2024 to 2025). "The genotypes of MGP polymorphisms (rs1800801, rs1800802, and rs4236) did not significantly affect stage of CKD, metabolic syndrome, and plasma MGP levels." (PMID 39246453, 2024).
Hepatic fibrosis (2 papers, 2022 to 2025). The presence of excessive fibrous connective tissue in the liver. "Additional studies will be required to clarify potential links between the effects of MGP on adipose and hepatic fibrosis." (PMID 40780446, 2025).
Hyperglycemia (2 papers, 2024 to 2025). An increased concentration of glucose in the blood. "This study identifies a previously unrecognized exosomal lncRNA-mediated pathway involving MALAT1, miR-143-3p, and MGP that regulates the response of vascular smooth muscle cells (VSMCs) to hyperglycemia." (PMID 41440015, 2025). "We hypothesized that these genes might be relevant to the systemic effects of hyperglycemia, and in particular, four genes were upregulated across many cell types and organs in STZ mice: the proteoglycan decorin (Dcn), gelsolin (Gsn), matrix Gla protein (Mgp), and metallothionein 1 (Mt1)." (PMID 38305779, 2024).
Hyperoxaluria (2 papers, 2017 to 2018). Increased excretion of oxalates in the urine. "Altogether, our data suggest a local defensive urothelial mechanism involving OPN and MGP macromolecules acting against crystal retention with a possible upregulation of MGP by hyperoxaluria or COM crystals as demonstrated in vitro in tubular cells." (PMID 30397242, 2018). "Results of our present study show that OPN, MGP, Fetuin B, Fn1, CD 44, Clusterin, Bikunin/AMBP genes are upregulated during hyperoxaluria and further increased with crystal deposition." (PMID 29091707, 2017).
kidney damage (2 papers, 2020 to 2023). "The main mechanism of the warfarin-related nephropathy is considered calcification of renal arteries induced by inhibition of vitamin K-dependent protein matrix gamma-carboxyglutamic acid (Gla/MGP)." (PMID 33166317, 2020).
lung diseases (2 papers, 2021 to 2024). "Vitamin K is also essential for the carboxylation of MGP, and insufficient levels of vitamin K can hinder MGP activation, potentially leading to lung damage in conditions such as SARS-CoV-2 pneumonia and other lung diseases, including COPD." (PMID 39371942, 2024).
malnutrition (2 papers, 2013 to 2018). Inadequate nutrition resulting from poor diet, malabsorption, or abnormal nutrient distribution. "For the first time in hemodialysis patients to our knowledge, we demonstrated that malnutrition (a high MQSGA score and a low level of serum albumin) was closely associated with arterial calcification and the expressions of BMP2 and MGP." (PMID 23506394, 2013). "Malnutrition is prevalent in hemodialysis patients and is associated with arterial calcification and the expressions of BMP2 and MGP in calcified radial arteries." (PMID 23506394, 2013). "However, whether malnutrition participates in the process of arterial calcification and associates with the expressions of BMP2 and MGP are not well understood." (PMID 23506394, 2013). "Using no phosphate binders may have been related to malnutrition, and hence a lower production of various proteins, including MGP and thereby dp-ucMGP." (PMID 30161193, 2018).
Osteochondrosis (2 papers, 2019 to 2025). Abnormal growth ossification centers in children. "However, Matrix gla protein (MGP) was proposed as a potential candidate gene for the development of osteochondrosis in pigs of the same breeds in another study." (PMID 41465565, 2025). "In addition, lower expression of MGP may lead to the development of osteochondrosis as a result of destitute blood and nutrient for the cartilage." (PMID 30617055, 2019). "It was reported that the absence of functional MGP might lead to osteochondrosis in animal models." (PMID 30617055, 2019).
pneumonia (2 papers, 2021 to 2023). An acute, acute and chronic, or chronic inflammation focally or diffusely affecting the lung parenchyma, caused by an infection in one or both of the lungs (by bacteria, viruses, fungi, or mycoplasma.). "Taking these data together, we propose a mechanism of pneumonia-induced vitamin K depletion, leading to a decrease in activated MGP and protein S, aggravating pulmonary damage and coagulopathy, respectively." (PMID 33023681, 2021). "Pneumonia‐induced extrahepatic VitK depletion could lead to accelerated elastic fiber damage and thrombosis in severe COVID‐19 due to impaired activation of MGP and endothelial protein S, respectively." (PMID 37051359, 2023).
PXE-like syndrome (2 papers, 2012 to 2017). "A somewhat similar convergence exists between the PXE-like syndrome in which GGCX mutations lead to insufficient MGP carboxylation (activation) and the classic inherited PXE." (PMID 23248644, 2012).
thyroid (2 papers, 2015 to 2024). "The positive associations between fT3 and dp-ucMGP and sKlotho suggest that synthesis of MGP and Klotho is influenced by thyroid hormones, and supports a link between non-thyroidal illness and alterations in calcification inhibitor levels." (PMID 26147960, 2015).